DACT1 (dishevelled binding antagonist of beta catenin 1)
Diseases named in the same sentence as DACT1 in open-access papers (continued):
Sharing a sentence is not in itself a finding about the gene and the disease.
cystic kidneys (1 paper, 2023). "One surviving Dact1-deficient female adult mouse had cystic kidneys, as did more than half of our patients with DACT1 variants, and vaginal agenesis leading to infertility." (PMID 36066768, 2023).
esophageal cancer (1 paper, 2017). A primary or metastatic malignant neoplasm involving the esophagus. "Frequent reduced expression of DACT1, DACT2 and DACT3 were found in esophageal cancer cell lines and the expression levels of DACT1 and DACT2 were reversed by 5-Aza-Dc." (PMID 28077137, 2017). "In the present study, we found the expression of DACT1, DACT2 and DACT3 were frequently silenced or decreased in esophageal cancer cell lines." (PMID 28077137, 2017). "In addition, the inhibition of proliferation and migration was further detected in TE1 and TE13 cells after treatment with 5-Aza-Dc or stable transfection of DACT1 or DACT2 plasmid, indicating the tumor suppressor role of DACT1 and DACT2 in esophageal cancer cell lines." (PMID 28077137, 2017).
Infertility (1 paper, 2023). "Infertility may particularly affect male patients with DACT1 variants, consistent with the finding of blind-ended vas deferens in Dact1-deficient male mice, because all DACT1 variants identified here were maternally inherited, as far as this could be determined." (PMID 36066768, 2023).
Intellectual disability (1 paper, 2023). "In some patients carrying DACT1 variants, malformations of the brain and/or intellectual disability were also observed." (PMID 36066768, 2023).
ischemic stroke (1 paper, 2017). A stroke disorder caused by obstruction of blood flow to the brain, due to thrombotic (local blood clot formation) or embolic (due to a blood clot or other material traveling from another site) event. "Nin, Dact1, and Rtn1, which are located underneath the linkage peak and contain one or more nontolerated nonsynonymous SNPs, have shown suggestive associations with increased risk of ischemic stroke or lipoprotein particle size." (PMID 28040783, 2017).
lymph node metastasis (1 paper, 2019). "The DACT1 gene promoter was hyper-methylated in 32 of 38 NPC patients with lymph node metastases." (PMID 31182157, 2019). "The DACT1 gene promoter was hyper-methylated in 32 of 38 cases of NPC with lymph node metastases; however, the DACT1 gene promoter were hyper-methylated in 7 of 24 cases of NPC without lymph node metastases." (PMID 31182157, 2019).
osteoarthritis (1 paper, 2023). A noninflammatory degenerative joint disease occurring chiefly in older persons, characterized by degeneration of the articular cartilage, hypertrophy of bone at the margins and changes in the synovial membrane. "LncRNA CRNDE relieved the progression of osteoarthritis via upregulation of dapper antagonist of catenin-1 (DACT1) by epigenetic modification and inactivation of Wnt/β-catenin pathway." (PMID 37779916, 2023).
ovarian carcinoma (1 paper, 2017). A malignant neoplasm originating from the surface ovarian epithelium. "To investigate whether DACT1 is implicated in ovarian cancer, we first examined its expression in several ovarian cancer cell lines by quantitative real-time RT-PCR." (PMID 28839145, 2017). "To elucidate the mechanism by which DACT1 suppresses ovarian cancer cell growth, we assessed the levels of the key mediators of canonical Wnt signalling, such as Dvl2 and β-catenin, in 3AO-DACT1." (PMID 28839145, 2017).
schizophrenia (1 paper, 2013). A major psychotic disorder characterized by abnormalities in the perception or expression of reality. "In sum, our results support a novel cell-autonomous postsynaptic role for Dact1, in cooperation with Dishevelled-1 and possibly Disrupted in Schizophrenia-1, in the formation of synapses on cortical interneuron dendrites." (PMID 23826333, 2013).
thyroid cancer (1 paper, 2022). "First, we verified the expression of 9 immune-related prognostic factors, AKAP12, APOC1, TIMP3, ADAMTS9, ANK2, HTRA3, SYNDIG1, ​​ADAMTS5 and DACT1, in 11 thyroid cancer cell lines in the CCLE database." (PMID 36591507, 2022).
Townes-Brocks syndrome (1 paper, 2021). Townes-Brocks syndrome (TBS) is a rare genetic disorder characterized by the triad of imperforate anus, dysplastic ears often associated with sensorineural and/or conductive hearing impairment, and thumb malformations. "In addition to the SALL1 gene, recent studies found that mutations in the Dishevelled Binding Antagonist Of Beta Catenin 1 (DACT1) gene located on chromosome 14q23 may also lead to TBS, which is called Townes-Brocks syndrome-2 (TBS2; 617466)." (PMID 33478437, 2021).
Townes-Brocks syndrome 2 (1 paper, 2025). "Besides, DACT1 variants have been associated with a phenotype known as Townes-Brocks syndrome 2 (MIM #617466), which causes mostly congenital anomalies of the kidney and urinary tract, possibly associated with skeletal, anorectal and genital anomalies." (PMID 40348827, 2025).
urothelial carcinoma (1 paper, 2012). A malignant neoplasm derived from the transitional epithelium of the urinary tract (urinary bladder, ureter, urethra, or renal pelvis). "The DACT1 gene was hypermethylated in 58.62% (17 out of 29) urothelial carcinomas, and only 25% (7 of 29) in healthy bladder tissue (P < 0.05)." (PMID 23554767, 2012). "Decreased expression of DACT1 was detected in 89.66% of urothelial carcinomas (26/29; P < 0.005)." (PMID 23554767, 2012).
valvular heart disease (1 paper, 2019). "Interestingly, we found a significant association between DACT1 expression and Cx43 in the patients with valvular heart disease (P=0.048, Spearman’s rho=0.370)." (PMID 31545578, 2019). "The relationship between DACT1 expression and β-catenin expression in the myocardium of patients with valvular heart disease." (PMID 31545578, 2019). "Very strong staining for DACT1 was detected in the normal human heart tissue, and decreased expression was observed in the myocardial tissue of the patients with valvular heart diseases." (PMID 31545578, 2019). "The relationship between DACT1 expression and connexin 43 (Cx43) expression in the myocardium of patients with valvular heart disease." (PMID 31545578, 2019). "The relationship between DACT1 expression in the myocardium and the cardiac rhythm of patients with valvular heart disease." (PMID 31545578, 2019). "In summary, we demonstrated for the first time that a lack of DACT1 was associated with AF and the degree of fibrosis in valvular heart disease." (PMID 31545578, 2019). "Furthermore, its expression was positively correlated with DACT1 cytoplasmic expression, suggesting that DACT1 may facilitate the extranuclear accumulation of β-catenin, which might serve as a structural protein in the myocardial cells of the valvular heart disease patients." (PMID 31545578, 2019).
tumor (19 papers, 2012 to 2025). "The Dapper1/Dpr1 (DACT1) gene is a tumor-associated gene that plays an important role in the regulation of tumor cell growth, proliferation, invasion, and metastasis." (PMID 31182157, 2019). "Since aberrant activation of Wnt signalling has been implicated in the pathogenesis of EOC and DACT1 can regulate Wnt signalling, we investigated whether DACT1 could regulate tumour growth by modulating Wnt signalling." (PMID 28839145, 2017). "DACT1 has been reported as a potential tumor marker associated with poor prognosis of NSCLC." (PMID 23497530, 2013). "Dysregulated DACT1 was associated with poor prognosis in tumor patients." (PMID 23497530, 2013). "Pathogenic variants of these genes were also identified, including tumor or posterior malformation in FZD4 (c.74G>T), ARRB2 (c.287A>C), and DACT1 (c.1561-1G>A) in humans and mice." (PMID 35008901, 2022). "Of note, DACT1 levels are abrogated in several GC cell lines by hypermethylation, whereas DACT1 protein abundance is reduced in GC tissues compared to adjacent non-tumor tissue." (PMID 32195251, 2020). "Taken together, our study report that miR-324-3p promotes tumor growth through targeting DACT1 and activation of Wnt/β-catenin pathway in HCC." (PMID 29029464, 2017). "Next, 3AO cells, which arise from a patient with primary mucinous EOC and express low endogenous levels of DACT1, were transfected with a lentivirus carrying full-length DACT1 (3AO-DACT1), grew slower and formed smaller tumours in nude mice compared to 3AO-NC." (PMID 28839145, 2017). "Both Western blot and real-time PCR data revealed a significant under-expression of DACT1 in HCC tissues compared to those in adjacent non-tumor tissues (P < 0.001)." (PMID 29029464, 2017). "And we focused on DACT1, which has been suggested to be a tumor suppresser in HCC by inhibiting Wnt/β-catenin signaling pathway." (PMID 29029464, 2017). "Based on the analysis results, we focused on DACT1, which had been described as a tumor suppressor in HCC." (PMID 29029464, 2017). "Our findings suggest that DACT1 functions as a tumour suppressor in type I EOC and highlight a potential new biomarker of cis-platinum response and a novel therapeutic target against type I EOC, especially against mEOC." (PMID 28839145, 2017). "As the Wnt/β-catenin signaling pathway plays a key role in tumor metastasis, the effect of DACT1 on cell migration was further analyzed." (PMID 23497530, 2013). "Together, these results clearly show that DACT1 stimulates cell proliferation and tumor growth by promoting the entry of cells into the cell cycle through increasing levels of β-catenin." (PMID 22470507, 2012). "Our data also suggest that other molecular mechanisms contribute to lower DACT1 expression in the tumor." (PMID 23554767, 2012). "The mean tumor volume was 2,068.78±561.57 mm3 in mice injected with HCT116 cells that expressed control siRNA, compared to the mean tumor volume in mice injected with HCT116 cells that expressed DACT1 siRNA (503.46±178.90 mm3)." (PMID 22470507, 2012). "Here, our observations show that the expression of DACT1 enhances cellular proliferation and promotes tumor growth and metastasis in the SW480, HCT116, LoVo and HT29 cell lines with or without APC or β-catenin mutations." (PMID 22470507, 2012). "The results suggest that increasing DACT1 methylation is correlated with tumor growth and progression." (PMID 23554767, 2012). "Relevantly, DACT1 promoter methylation was correlated with tumor size and metastasis." (PMID 32195251, 2020). "Therefore, our findings highlighted the prospective role of H1FX-AS1 as a new prospective tumor suppressor gene and a prognostic predictor in CC patients, and a ceRNA of miR-324-3p to inhibit DACT1 mediated CC progression." (PMID 32760225, 2020). "Also, the overexpression of DACT1 -an antagonist of Wnt/β-catenin pathway—has been able to inhibit tumor growth and cisplatin resistance in type I epithelial ovarian cancer." (PMID 30894224, 2019).
tumor (continued). "In summary, in NPC tissues and cells, DACT1 gene expression was related to the methylation status, which can be changed by regulating the methylation status and regulate the growth and invasion of tumor cells." (PMID 31182157, 2019). "Overall, we concluded that miR-324-3p could promote tumor growth through targeting DACT1 and activation of Wnt/β-catenin pathway in HCC." (PMID 29029464, 2017). "We next investigated whether DACT1 could counteract Wnt/β-catenin signaling for its tumor-suppressive function." (PMID 23497530, 2013). "DACT1 gene hypermethylation was closely related to tumor size, grade and stage (P < 0.05)." (PMID 23554767, 2012). "Recent studies have shown that DACT1 is a tumor-related gene that may regulate tumor cell growth, proliferation, invasion, and metastasis by increasing the expression of beta-catenin, affecting the Wnt signaling pathway, and regulating the cell cycle and apoptosis." (PMID 31182157, 2019). "Dapper homolog 1 (DACT1), located on chromosome 14q23 1 region, is a recently identified tumor suppressor gene that exhibits downregulation in various types of malignant tumors." (PMID 40356725, 2025). "Over-expression of DACT1 suppressed cell proliferation of 3AO, and when transplanted into nude mice, 3AO-DACT formed smaller tumours." (PMID 28839145, 2017). "However, it was shown that promoter methylation of DACT1 and DACT2 may not be a common event in oral squamous cell carcinoma 86, suggesting promoter methylation of DACTs has the tumor cell-specific, and the precise mechanism of this gene family inactivation need to be further studied." (PMID 35864965, 2022).
cancer (16 papers, 2012 to 2025). A tumor composed of atypical neoplastic, often pleomorphic cells that invade other tissues. "Beyond its involvement in cancer, DACT1 has been implicated in other diseases, including human muscle disorders and type 2 diabetes mellitus." (PMID 40356725, 2025). "Furthermore, based on the evolutionary and functional conservation of Wnt signaling molecules, as well as the human chromosomal localization of DACT1, the DACT1 gene is also predicted to be a potent cancer-associated gene." (PMID 22470507, 2012). "Although some studies have shown associations between DACT1 expression and cancer, the function of DACT1 in the WNT/β-catenin signaling pathway remains unclear." (PMID 22470507, 2012). "DACT1, VRK2, MELTF, and FGF12 have been implicated in cancers other than CC, and PRICKLE2 has been reported to correlate with CC." (PMID 32408396, 2020). "Based on Evolutionary and functional conservation of Wnt signaling molecules as well as human chromosomal localization, DACT1 and DACT2 genes were predicted to be potent cancer-associated genes." (PMID 25375359, 2014). "The promoter of the DACT1 gene in 17 out of 29 (58.62%) cancer tissue specimens and in 7 out of 29 (25%) normal tissues was hypermethylated (P < 0.05)." (PMID 23554767, 2012). "All of these evidences strongly indicate that DACT1 may serve as a predictive factor for the prognosis of cancer, and the function of DACT1 may be dependent on cellular context." (PMID 35864965, 2022). "Among three members in the DACT family, DACT1 is the best investigated in various types of cancer." (PMID 35864965, 2022). "Furthermore, in the sections of five cases with mEOC, the expression of DACT1 in benign lesion was observed significantly stronger than that in cancer tissues on the same section." (PMID 28839145, 2017). "Many studies have demonstrated that DACT1 is a key mediator in the negative regulation of the Wnt/β-catenin signaling pathway, whereas abnormal activation of this signaling pathway participates in the process of cancer progression." (PMID 23554767, 2012). "In several studies, low levels of DACT1 were described in NSCLC, while its over-expression has also been documented in other cancer types." (PMID 34065402, 2021).
cardiac disease (1 paper, 2022). "It is, thus, proposed that the altered expression pattern of DACT1 and β-catenin in the myocardium may contribute to the progression of cardiac disease." (PMID 35510412, 2022). "There is, thus, an unknown mechanism between cytoskeleton and gap junctions in cardiac disease in which DACT1 might play a role, but little is known about it, especially regarding the role of DACT1 in human normal myocardial cells due to a lack of suitable research models." (PMID 35510412, 2022).
myopathy (1 paper, 2023). A disease of the muscle in which the muscle fibers do not function properly. "Furthermore, RNA-seq data showed alterations in several genes involved in Wnt signaling, such as APC, DACT1, DKK2, DVL2, and WNT4, emphasizing an important role for Wnt signaling in WB myopathy." (PMID 38130476, 2023).
DACT1 also shares sentences with these, for which no sentence is quoted: diabetic nephropathy (2 papers); infection (2); leukemia (2); prostate carcinoma (2); squamous cell carcinoma (2); adenocarcinoma (1); asthma (1); B-cell chronic lymphocytic leukemia (1); Cachexia (1); cardiac arrhythmia (1); caudal regression syndrome (1); colorectal tumors (1); craniorachischisis (1); cystic kidney disease (1); diabetes (1); ductal carcinoma in situ (1); fatty liver (1); gastrointestinal stromal tumours (1); head and neck cancer (1); head and neck squamous cell carcinoma (1); Hydroureter (1); hyperhomocysteinemia (1); invasive ductal carcinoma (1); kidney malformations (1); medullary cystic kidney disease (1); Megacystis (1); nephronophthisis (1); oral squamous cell carcinomas (1); polycystic kidney disease (1); type 2 diabetes (1).